KMT2D (lysine methyltransferase 2D)
Diseases named in the same sentence as KMT2D in open-access papers (continued):
Sharing a sentence is not in itself a finding about the gene and the disease.
adenocarcinoma (3 papers, 2021 to 2026). A common cancer characterized by the presence of malignant glandular cells. "Here, we identify loss of the histone methyltransferase KMT2D as a critical event that disrupts adenocarcinoma lineage fidelity and promotes squamous transition." (PMID 41507359, 2026). "The other genes that were much more mutated in SCC (with estimated mutation proportion in SCC and in adenocarcinoma, respectively) were LRP1B (23%, 10%), KMT2D (16%, 7%), FAT1 (15%, 5%), CDKN2A (12%, 2%), NOTCH1 (10%, 3%), and NFE2L2 (10% and 1%)." (PMID 34645806, 2021).
genetic disease (2 papers, 2020 to 2023). "It is consistent with the pathogenesis of KS, an autosomal dominat genetic disease caused by KMT2D gene mutation." (PMID 38115267, 2023).
KMT2D also shares sentences with these, for which no sentence is quoted: microcephaly (5 papers); Beckwith-Wiedemann syndrome (4); KBG syndrome (4); Kleefstra syndrome (4); Burkitt lymphoma (3); humoral immune deficiency (3); immune disorder (3); Mowat-Wilson syndrome (3); Wiedemann-Steiner syndrome (3); Alagille syndrome (2); alveolar rhabdomyosarcoma (2); breast tumors (2); choanal atresia (2); chronic myelogenous leukemia, BCR-ABL1 positive (2); diabetes (2); epilepsy (2); Floating-Harbor syndrome (2); growth deficiency (2); hematological malignancies (2); non-small cell lung carcinoma (2); pheochromocytoma (2); renal dysplasia (2); sarcoma (2); Sotos syndrome (2); Adams-Oliver syndrome (1); adenoma (1); amyotrophic lateral sclerosis (1); anal carcinoma (1); antibody deficiency (1); Aortic Valve Disease 1 (1).
A further 128 diseases each share a sentence with KMT2D in 1 paper.